RBM3 (RNA binding motif protein 3)
Diseases named in the same sentence as RBM3 in open-access papers (continued):
Sharing a sentence is not in itself a finding about the gene and the disease.
breast carcinoma (15 papers, 2010 to 2025). "In breast cancer, a leading cancer type in women, RBM3 is overexpressed and has been associated with favorable clinicopathological parameters in two breast cancer cohorts." (PMID 28118608, 2017). "We have previously reported that expression of the RNA- and DNA-binding protein RBM3 is associated with a good prognosis in breast cancer and ovarian cancer." (PMID 21777469, 2011). "Having previously demonstrated that RBM3 was associated with a less aggressive breast cancer phenotype we sought to examine the relationship between RBM3 mRNA and protein expression and clinicopathological characteristics in two independent EOC cohorts." (PMID 20727170, 2010). "In breast cancer, nuclear RBM3 expression was associated with favourable clinicopathological parameters, including hormone receptor status." (PMID 20727170, 2010). "We recently demonstrated that increased expression of the RNA-binding protein RBM3 is associated with a favourable prognosis in breast cancer." (PMID 20727170, 2010). "LINC00096 directly interacts with miR-383 and promotes proliferation and invasion by regulating the miR-383-5p/RBM3 pathway in breast cancer in humans." (PMID 38643124, 2024). "Other genes were associated with cell adhesion and migration of breast cancer cell [DUOXA1 and PGAM1], prognosis of breast cancer [PGK1 and KLK10], or clinical outcome in breast cancer [RBM3 and AQP5]." (PMID 34497807, 2021). "RBM3 regulates ARPC2 in a post-transcriptional 3′UTR-binding manner to promote breast cancer cells proliferation and migration." (PMID 34804951, 2021). "It has demonstrated high expression of RBM3 is correlated with decreasing tumor progression, recurrence and increasing disease free survival in breast cancer." (PMID 28118608, 2017). "Breast cancer is the leading cancer type in women, and RBM3 is overexpressed in this cancer, with a direct correlation of RBM3 expression level and improved clinical outcome." (PMID 27147467, 2016). "In our previous study in breast cancer, the favourable prognostic impact of RBM3 was assessed by IHC in two independent patients cohorts using a polyclonal, monospecific antibody, initially developed within the HPA programme." (PMID 20727170, 2010). "RBM3 promotes the proliferation and metastasis of human breast cancer cells." (PMID 34804951, 2021). "Moreover, the overexpression of RNA-binding motif protein 3 (RBM3) facilitated proliferation and drug resistance via the β-catenin pathway in colon cancer cells; however, it indicated a favorable prognosis in breast cancer." (PMID 33460399, 2021). "The potential clinical relevance of this is however less evident as the beneficial effect of high RBM3 expression in breast cancer was independent of tamoxifen treatment." (PMID 20727170, 2010). "Apart from our previous study in breast cancer, there are to our knowledge no other published data on the prognostic impact of tumor-specific RBM3 expression in human cancer." (PMID 20727170, 2010). "Furthermore, analysis of the tumor specimens in Cohort II using the antibody that was used in the breast cancer study yielded concordant results regarding the prognostic impact of tumor-specific RBM3 expression (data not shown)." (PMID 20727170, 2010).
colorectal cancer (14 papers, 2010 to 2024). A primary or metastatic malignant neoplasm that affects the colon or rectum. "Colorectal cancer is the most common type of cancer of the digestive system, and a high level of RBM3 expression is associated with improved prognosis, whereas a loss of RBM3 expression is associated with poor prognosis and right-sided localization." (PMID 27147467, 2016). "Our study demonstrates that the 3-biomarker classifier, incorporating H2BUB1, RBM3 and Ki-67, is an effective tool for predicting survival outcomes in patients with colorectal cancer." (PMID 39335194, 2024). "It is described in that, that over-expression of RBM3 has subsequent effects on epithelial proliferation and stemness in colorectal cancer." (PMID 37286944, 2023). "The RNA binding protein, RBM3, promotes the stemness of colorectal cancer cells by enhancing β‐catenin activity." (PMID 33687144, 2021). "In colorectal cancer, RBM3 has previously been shown to stabilize the mRNA levels of COX-2 and IL-8." (PMID 29464064, 2018). "In line with RBM3 down-regulated led to activation of both Chk1 and Chk2 in colorectal cancer cell lines." (PMID 28118608, 2017). "In colorectal cancer cells, RBM3 induces stemness through a mechanism involving suppression of GSK3β kinase activity, thereby enhancing β-catenin signaling." (PMID 27147467, 2016). "The gene RBM3 is a well-known gene in terms of prognostication of colorectal cancer." (PMID 37286944, 2023). "In colorectal cancers, RBM3 enhances Wnt/β-catenin signaling mediated by inactivation of GSK3β." (PMID 28118608, 2017). "However, the strong predictive value of high RBM3 expression with regard to adjuvant treatment is in line with previous findings of RBM3 being predictive of response to platinum-based chemotherapy in epithelial ovarian cancer and colorectal cancer." (PMID 29464064, 2018). "Contrasting in vitro data have also been published, whereby RBM3 has been proposed to be a proto-oncogene stabilizing COX-2 mRNA levels and protecting against mitotic catastrophe in colorectal cancer cell lines." (PMID 20727170, 2010).
ovarian carcinoma (13 papers, 2010 to 2025). A malignant neoplasm originating from the surface ovarian epithelium. "The here observed inverse association of MCM3 and RBM3, both regarding their tumour-specific expression and impact on survival, is in line with previous in vivo and in vitro observations in ovarian cancer." (PMID 22805320, 2012). "In ovarian cancer, an inverse association was found between expression of RBM3 and the minichromosome maintenance 3 (MCM3) gene and protein." (PMID 22805320, 2012). "Here, we present data from two independent patient cohorts demonstrating that expression of the RNA-binding protein RBM3, both at the mRNA and protein levels, is associated with a good prognosis in epithelial ovarian cancer." (PMID 20727170, 2010). "In light of the recently proposed association between RBM3 and DNA integrity in ovarian cancer, it could be speculated that RBM3 might play an important role in promoting early stages of tumourigenesis by interfering with the anti-cancer barrier provided by various DNA damage checkpoint mechanisms." (PMID 21955582, 2011). "To date, there remains a lack of large-scale, systematically scored, tissue-based analyses evaluating the prognostic impact of RBM3 in epithelial ovarian cancer." (PMID 40506997, 2025). "Further multicenter validation and mechanistic studies are warranted to clarify RBM3’s functional role and therapeutic potential in ovarian cancer." (PMID 40506997, 2025). "Given the recognized heterogeneity of ovarian cancer, we further conducted subgroup analyses stratified by histologic subtype to evaluate the prognostic value of RBM3 within individual tumor types." (PMID 40506997, 2025). "Although RBM3 can exhibit cytoplasmic localization in certain contexts, immunohistochemical evaluation in this study revealed predominantly nuclear staining in ovarian carcinoma tissues." (PMID 40506997, 2025). "Although previous studies have reported a correlation between RBM3 expression and clinical outcomes in ovarian cancer, these investigations have been limited by small sample sizes or heterogeneous scoring systems." (PMID 40506997, 2025). "In epithelial ovarian cancer cell lines, RBM3 expression silencing resulted in decreased sensitivity to cisplatin." (PMID 34804951, 2021). "In contrast with previous studies on e.g. epithelial ovarian cancer, high mRNA levels of RBM3 were found to signify a significantly shorter survival." (PMID 29464064, 2018). "High expression of the RNA-binding motif protein 3 (RBM3) has been shown to correlate, with prolonged survival in several malignant diseases and with the benefit of platinum-based chemotherapy in ovarian cancer." (PMID 28800641, 2017). "RBM3 expression has also been demonstrated to correlate with sensitivity to platinum-based chemotherapy in ovarian cancer in vivo and in vitro." (PMID 25811459, 2015). "In this study we used a monoclonal antibody against RBM3, which was also used in our previous study on ovarian cancer." (PMID 21777469, 2011). "RBM3 expression was also examined in vitro using the cisplatin sensitive ovarian cancer cell line A2780 and its cisplatin resistant derivative A2780-Cp70." (PMID 20727170, 2010). "The aim of this study was to examine the prognostic value of RBM3 mRNA and protein expression in epithelial ovarian cancer (EOC) and the cisplatin response upon RBM3 depletion in a cisplatin-sensitive ovarian cancer cell line." (PMID 20727170, 2010). "Immunoblotting and IHC were used to examine the expression of RBM3 in a cisplatin-resistant ovarian cancer cell line A2780-Cp70 and its cisplatin-responsive parental cell line A2780." (PMID 20727170, 2010). "Future investigations integrating molecular stratification may help elucidate whether RBM3’s expression correlates with specific genomic or transcriptomic subtypes of ovarian cancer and clarify its utility as a subtype-specific biomarker." (PMID 40506997, 2025).
ovarian carcinoma (continued). "High RBM3 expression was significantly associated with favorable clinicopathological characteristics, including a low FIGO stage, absence of distant metastasis, and a favorable histologic subtype in epithelial ovarian cancer." (PMID 40506997, 2025). "Compared to previous studies that have reported the prognostic relevance of RBM3 in ovarian cancer, our study adds value by utilizing one of the largest TMA-based cohorts to date, applying a statistically validated cutoff scoring system, and focusing on a reproducible nuclear scoring method." (PMID 40506997, 2025). "In this study, we sought to address this gap by analyzing RBM3 expression using immunohistochemistry on a well-characterized, single-institution cohort of 183 epithelial ovarian cancer cases, applying a statistically validated nuclear scoring algorithm to stratify RBM3 expression levels." (PMID 40506997, 2025). "High RBM3 expression has been shown to signify an improved prognosis in solid cancers including malignant melanoma, colorectal, urothelial bladder, breast, and epithelial ovarian cancer." (PMID 35109796, 2022). "In addition, siRNA-mediated down-regulation of RBM3 in epithelial ovarian cancer cells has been demonstrated to confer a reduced sensitivity to platinum-based chemotherapy." (PMID 29464064, 2018). "Silencing RBM3 decreases the sensitivity to cisplatin in ovarian cancer cell lines." (PMID 28800641, 2017). "RBM3 levels were higher in cisplatin-sensitive than cisplatin-resistant ovarian cancer cells." (PMID 28118608, 2017). "Moreover, RBM3 expression has been demonstrated to correlate with sensitivity to cisplatin treatment in ovarian cancer in vitro." (PMID 25811459, 2015). "We initially confirmed lower RBM3 protein levels in the cisplatin-resistant ovarian cancer cell line A2780-Cp70 compared to their parental cisplatin-sensitive A2780 cells and using RNAi techniques, we demonstrated that silencing of RBM3 led to a decreased cisplatin response in ovarian cancer cells." (PMID 20727170, 2010). "Furthermore, we show that decreased RBM3 expression confers reduced platinum sensitivity in ovarian cancer cells." (PMID 20727170, 2010). "It was suggested that RBM3 might be a useful therapeutic predictor in epithelial ovarian cancer." (PMID 34804951, 2021). "This is in line with a previous study on ovarian cancer, wherein RBM3 levels were found to be significantly higher in parental A2780 ovarian cancer cells compared to their cisplatin-resistant derivative, and reduced cisplatin-sensitivity upon RBM3 knockdown in the former." (PMID 29464064, 2018). "Specifically, RBM3 expression may aid in refining risk stratification models and guide prognostic assessment in patients with histologically favorable or early-stage epithelial ovarian cancer, particularly where advanced molecular testing is not readily available." (PMID 40506997, 2025). "In epithelial ovarian cancer (EOC), RBM3 overexpression is correlated with a favorable prognosis." (PMID 28118608, 2017). "While RBM3 expression alone may not function as an independent prognostic marker, our findings support its relevance as a complementary biomarker that reflects favorable biological behavior in epithelial ovarian cancer." (PMID 40506997, 2025).
neuroblastoma (9 papers, 2017 to 2024). Neuroblastoma (NB) is the most common solid, extracranial childhood tumor. "RBM3 has been reported to promote the development of colitis-associated cancer or enhance migration ability in neuroblastoma cell lines." (PMID 31546614, 2019). "Alleviation of oxidative stress has been attributed to CIRBP in mouse testes, hepatocytes, the neuroblastoma cell line neuro2a, and in rat cortical neurons, and to RBM3 in human SH-SY5Y neuroblastoma cells and C2C12 mouse myoblasts." (PMID 31443506, 2019). "Conversely, the overexpression of RBM3 reduces MPP+-induced apoptosis in SH-SY5Y neuroblastoma cells." (PMID 29773975, 2018). "In this study, we demonstrated that cold shock protein RBM3 protects neuroblastoma cells SH-SY5Y from MPP+-induced apoptosis." (PMID 29773975, 2018). "In our studies, RBM3 localized to SICs and to protrusions in the B104 neuroblastoma cell line that are morphologically very similar to the invadopodia of MDA-MB231 cells." (PMID 29743635, 2018). "RBM3 was present in SICs formed around the periphery of newly adherent cells early (30 minutes) after plating of B104 neuroblastoma cells and HeLa epithelial adenocarcinoma cells onto glass, collagen, and fibronectin." (PMID 29743635, 2018). "In conclusion, we have demonstrated that RBM3 confers neuroprotective effects in MPP+-induced apoptosis in human neuroblastoma cells." (PMID 29773975, 2018). "The present study demonstrated that mild hypothermia protects neuroblastoma cells from NO-induced apoptosis and that this protection is mediated by the cold-inducible protein RBM3." (PMID 28134320, 2017). "The most important finding of the present study is that RBM3 executes its neuroprotective effect via inhibition of NO-induced p38 signaling in neuroblastoma cells." (PMID 28134320, 2017). "In summary, the present study indicates that the cold-inducible protein RBM3 prevents NO-induced apoptosis in human neuroblastoma cells by modulating p38 signaling and miR-143." (PMID 28134320, 2017). "In this study, we hypothesized that mild hypothermia protects human neuroblastoma SH‐SY5Y cells from ROT‐induced neurotoxicity (in vitro model of PD) via the action of RBM3." (PMID 31436914, 2019). "Hypothermia and RBM3 prevent apoptosis in neuroblastoma cells, indicating that people could utilize RBM3 induction or RBM3 agonist to improve neurological disorders in injured brain areas." (PMID 28134320, 2017). "In multiple cell types, RBM3 was observed within SICs formed shortly after plating onto several substrates, and within cellular protrusions – such as growth cone-like extensions in neuroblastoma cells and membrane blebs in myoblasts – that developed during the course of cell spreading and migration." (PMID 29743635, 2018). "RBM3 rather than mild hyperthermia prevents MPP+-apoptosis in neuroblastoma cells, thereby suggesting that RBM3-specific induction/overexpression might be used as a strategy for the treatment of neurodegenerative diseases." (PMID 29773975, 2018).
Alzheimer disease (7 papers, 2018 to 2024). A progressive, neurodegenerative disease characterized by loss of function and death of nerve cells in several areas of the brain leading to loss of cognitive function such as memory and language. "Thus, we were unable to conclude whether Rbm3’s association with neuronal vulnerability is common to prion and Alzheimer’s disease." (PMID 39580485, 2024). "Blocking RBM3 upregulation by RNAi prevented neuroprotective and cognitive improvements induced by hibernation-like cooling in transgenic mice afflicted with Alzheimer's disease (5XFAD) or inoculated with prions to induce severe neurodegeneration (tg37 mice)." (PMID 30802174, 2019). "RBM3 overexpression in the brain decreased Alzheimer's disease neuropathology and cognitive impairment in 5XFAD mice." (PMID 30802174, 2019). "The cold shock protein RBM3 can mediate mild hypothermia-related protection in neurodegeneration such as Alzheimer's disease." (PMID 29773975, 2018). "Our promising results in mice support the possibility that RBM3‐inducing ASOs might also deliver neuroprotection in humans in conditions ranging from acute brain injury to Alzheimer's disease." (PMID 36946385, 2023). "Taken together, hypothermia pre‐treatment reverses TBI‐induced chronic AD‐like pathology and behaviour deficits in RBM3 expression dependent manner, RBM3 may be a potential target for neurodegeneration diseases including Alzheimer disease." (PMID 32648620, 2020). "Inducing endogenous RBM3 expression by hypothermia or overexpression by AAV mediation in vivo improves memory deficits and loss of synapses in prion and Alzheimer‐type mice, suggesting that RBM3 may be a potential target for preventing neurodegeneration disease including Alzheimer disease." (PMID 32648620, 2020). "We did not detect neuronal RBM3 expression in the Leng or Grubman Alzheimer’s disease datasets, possibly because it is more challenging to detect low-abundance transcripts with single-nucleus RNA sequencing." (PMID 39580485, 2024).
hepatocellular carcinoma (7 papers, 2013 to 2022). A malignant tumor that arises from hepatocytes. "RNA-binding protein 3 (RBM3) dynamically adjusts the proliferation of hepatocellular carcinoma cells by regulating the production of SCD-circRNA2 encoded by the 3′-UTR of the stearoyl-CoA desaturase (SCD) gene." (PMID 33928139, 2021). "RBM3: The splicing factor RBM3 shows higher expression in hepatocellular carcinoma and is reported to help liver cancer cell proliferation and survival." (PMID 34449657, 2021). "Rbm3 was also upregulated in two independent cohorts of human liver carcinomas, especially in ICCs." (PMID 31546614, 2019). "Overexpression of RBM3 in hepatocellular carcinoma (HCC) positively correlates to levels of SCD-circRNA 2 generated from the stearoyl-CoA desaturase (SCD) gene." (PMID 34449657, 2021). "Furthermore, RBM3 could promote the growth and proliferation of hepatocellular carcinoma (HCC) cells in the stearoyl-CoA desaturase (SCD)-circRNA-2-dependent manner by control SCD-circRNA-2 formation." (PMID 34804951, 2021). "As yet there are no reports on the translation initiation efficiency of the Rbm3 IRES in human Huh7 and HepG2 hepatoma cells." (PMID 23589756, 2013).